WNT5A (Wnt family member 5A)
Diseases named in the same sentence as WNT5A in open-access papers (continued):
Sharing a sentence is not in itself a finding about the gene and the disease.
melanoma (continued). "Studies have also shown that WNT5A can induce EMT and cell motility in lung cancer, prostate cancer, and melanoma." (PMID 37173306, 2023). "First, we showed that JI130 and MEL56 inhibit cell migration in two invasive melanoma cell lines (MM029 and MM165) and downregulate the mRNA expression of the main EMT/invasion markers such as AXL, EGFR, MET, ZEB1, WNT5A, TGFβ, SNAI1, TWIST and MMPs." (PMID 37508519, 2023). "AXL overexpression in melanoma cells reduced the expression of MER and decreased metastatic colonies with unchanged WNT5A, implying that AXL is downstream of WNT5A." (PMID 36646673, 2023). "In a subset of melanoma tissues with low expression of tumor antigens such as MART-1, the expression of WNT5A is increased." (PMID 36982422, 2023). "In melanoma patients undergoing treatment with BRAF inhibitors (BRAFi), WNT5A expression in tumor tissues correlates with therapy response." (PMID 36982422, 2023). "BRAF mutant melanoma cell lines resistant to the BRAFV600E inhibitor PLX4720 have been shown to upregulate WNT5A, and their sensitivity was restored by WNT5A depletion." (PMID 36539575, 2023). "Data reported in the literature have shown that WNT5A can regulate the secretion of IL-6 and CCL2 in other types of cancer, including melanoma and non–small cell lung cancer." (PMID 37607007, 2023). "WNT5A promotes epithelial-mesenchymal transition (EMT)-like changes in breast cancer, gastric cancer, pancreatic cancer, ovarian cancer, and malignant melanoma The transcription factor SNAIL is considered a key stimulator of the EMT." (PMID 35595735, 2022). "S100B, VEGF (vascular endothelial growth factor), IGF-1R (the insulin-like growth factor 1 receptor), Wnt-5a, LDH (lactate dehydrogenase), and MIA (melanoma inhibitory activity) have all been shown to correlate positively with prognosis in CM." (PMID 35982458, 2022). "Inhibition of MARCKS phosphorylation with a MARCKS-inhibitory peptide abolishes WNT5A-mediated melanoma cell invasion, suggesting that MARCKS is a crucial promoter of metastasis in melanoma and a candidate anti-metastatic target in melanoma patients." (PMID 36230850, 2022). "Akt is a well known effector of the Wnt5a pathway and both Wnt5a and ROR1 were consistently shown to promote Akt phosphorylation in several tumor types, including melanoma." (PMID 34774050, 2021). "Wnt Family Member 5A (WNT5A) regulates the release of EVs containing the immunomodulatory cytokine IL-6 and proangiogenic factors IL-8, VEGF, and MMP2 from melanoma cells (MeWo, SKmel28, A2058, A375, and HTB63)." (PMID 34685720, 2021). "In mouse splenic pDCs Wnt5a was found to upregulate the surface expression of indoleamine 2,3-dioxygenase-1 (IDO), which plays a significant role in DC tolerogenesis in melanoma." (PMID 33919546, 2021). "In response to a variety of environmental stimuli, the extracellular ligand WNT5A interacts with ROR2 and Frizzled (Fzd)-family receptors, resulting in AP-1 activation and subsequently promotes melanoma cell invasion." (PMID 34604096, 2021). "Reduced WNT5a signaling clearly had opposite effects on Rho activity levels in WM852 and HTB63 melanoma cells." (PMID 33969605, 2021). "A previous study in Human melanoma cell lines (A2058 and HTB63 showed a positive correlation between Wnt5a and lactic dehydrogenase expression, indicating the role of Wnt5a in glycolytic flux stimulation in cancer cell metabolism." (PMID 34178477, 2021). "In agreement with our observations, WNT5a has been shown to increase Vimentin and CD44 to enhance motility of melanoma cells and nasopharyngeal carcinoma via the Ca2+ signaling pathway." (PMID 32546756, 2020). "Our results showed that both a PKC inhibitor and a ROCK inhibitor inhibited approximately 50% of WNT5A-induced MARCKS phosphorylation in A2058 and A375 melanoma cells compared to the vehicle-stimulated controls." (PMID 32033033, 2020).
melanoma (continued). "For example, in melanoma cells, ROR2-FLNA interaction is critical for WNT5A-induced JNK phosphorylation, cytoskeleton remodeling, and cell migration, and WNT5A-ROR2 binding induces calpain expression and its cleavage of FLNA leading to increased invasiveness." (PMID 33134326, 2020). "Wnt signaling, and WNT5A in particular, has been shown to mediate EMT in melanoma and in lung cancer." (PMID 31694854, 2020). "Reducing WNT5A by siRNA in this model activated canonical WNT signaling and provoked cell death, counteracting melanoma formation." (PMID 32238882, 2020). "For instance, WNT5a increased Vimentin expression, but also decreased E-cadherin via activation of PKC pathway in melanoma cells." (PMID 32546756, 2020). "The WNT5A-mediated increase in total MARCKS expression was statistically significant in A2058 cells after 1 h and in A375 melanoma cells after 3 h of treatment with rWNT5A." (PMID 32033033, 2020). "A high level of WNT5A promotes the resistance to vemurafenib, highlighting the opposing roles of different WNT pathways in melanoma." (PMID 32659938, 2020). "We used a highly sensitive WST‐1 cell proliferation assay to assess the antiproliferative effect of BRAFi treatment following direct inhibition of IL‐6 and WNT5A signalling in HTB63‐R and A375‐R BRAFi‐R melanoma cell lines." (PMID 30582770, 2019). "Based on our present finding that IL‐6 and WNT5A independently mediate their effects on the invasive migration of BRAFi‐R melanoma cells, we investigated whether and how elevated IL‐6 secretion and WNT5A expression translated into increased BRAFi‐R melanoma cell migration and invasion." (PMID 30582770, 2019). "We confirmed the development of BRAFi resistance in our BRAFi‐treated melanoma cell lines by demonstrating reduced sensitivity to BRAF inhibitors, increased ERK1/2 activity and increased WNT5A expression." (PMID 30582770, 2019). "These and other studies indicate the presence of a third subpopulation in melanoma that expresses MITF, AXL, and WNT5A simultaneously." (PMID 29881716, 2018). "The aim of the current study was to explore the existence of a WNT5A-IL-6 positive feedback loop in malignant melanoma cells and to investigate whether dual interference with this loop would be a more effective therapeutic means to obstruct melanoma cell migration and invasion." (PMID 27191257, 2016). "WNT-5A induces the release of IL-6, MMP2, and vascular endothelial growth factor (VEGF) containing exosomes from melanoma cells in a Ca2+- and CDC42-dependent process that requires cytoskeletal reorganization." (PMID 26514730, 2016). "In contrast, WNT5A has been shown to positively drive EMT-like changes in gastric cancer, pancreatic cancer, ovarian cancer and malignant melanomas, where WNT5A acts as a tumor promoter." (PMID 27623766, 2016). "Wnt5a was found to be highly upregulated in a subset of BRAF inhibitor (BRAFi)-resistant melanoma tumors and in BRAFi-resistant melanoma cells derived in vitro." (PMID 27571105, 2016). "Next, we selected three melanoma cell lines—WM852, HTB63 and A375—that are phenotypically classified as invasive by the HOPP algorithm, and compared their levels of WNT5A and IL-6 mRNA/protein expression." (PMID 27191257, 2016). "It has been shown that sustained or increased expression of Wnt5A and/or ROR2 affects the invasive properties of several types of tumor cell, including melanoma, osteosarcoma, renal cell carcinoma, prostate carcinoma, gastric cancer and pancreatic cancer." (PMID 28536612, 2016). "The three melanoma cell lines (WM852, HTB63 and A375) studied expressed different levels of WNT5A protein and secreted different amounts of IL-6." (PMID 27191257, 2016). "By stimulating cells with recombinant WNT5A (rWNT5A), the authors demonstrated that resistance to BRAFi (i.e., PLX4720) increased two-fold in the BRAFi sensitive melanoma cell line 451 LU." (PMID 26393652, 2015).
melanoma (continued). "In agreement, we showed that the melanoma cell line A2058 upregulates WNT5A in response to TGFβ exposure and that exogenous Wnt-5a in turn, increased their invasive potential." (PMID 25755924, 2015). "WNT5A suppresses MITF and its downstream effector MART-1 (melanoma antigen recognized by T cells-1), which has also been positively correlated with melanoma cell migration." (PMID 26393652, 2015). "For example, Wnt5a can signal through frizzled receptor (Fz) 5 and thereby activate protein kinase C (PKC) in malignant melanomas." (PMID 25823923, 2015). "WNT5A expression is inversely correlated with MITF in proliferative and invasive melanoma phenotypes." (PMID 26393652, 2015). "Our recent study on melanoma cells demonstrated that IL-6 can regulate expression levels of WNT5A in a p38α MAPK-dependent manner, thereby regulating melanoma cell migration." (PMID 26393652, 2015). "The melanoma cell lines WM239A, UACC903, M93-047 and FS5 were found to secrete increasing levels of Wnt5a respectively." (PMID 26029828, 2015). "Nevertheless, this indicates that a third ‘class’ of melanoma cells exists where a particular intracellular signalling permits the co‐existence of MITF with AXL and WNT5A, which otherwise is mutual exclusive." (PMID 25818589, 2015). "Applying this model to the MITF‐positive and MITF‐negative populations would predict that melanoma cells reversibly switch between AXL‐/WNT5A‐ and AXL+/WNT5A+ cell populations." (PMID 25818589, 2015). "Given that IL-6 positively regulated the Wnt5a expression through the p38α-MAPK pathway in melanoma, we draw the reasonable inference that CD146 probably drives melanoma cell motility through the CD146-IL-6-p38α-MAPK- Wnt5a-WRAMP pathway." (PMID 25685061, 2015). "We show that WNT5A signaling induces a Ca2+-dependent release of exosomes containing the immunomodulatory and pro-angiogenic proteins IL-6, VEGF and MMP2 in melanoma cells." (PMID 24766647, 2014). "In our study, HH044 downregulated WNT5A, a contributor to Hedgehog signaling and a known druggable target for melanoma, and nNOS inhibition did not have a direct effect on Notch1 or Notch2 expression alone." (PMID 40574005, 2025). "Of note, changes in β-Catenin dependent (WNT3A driven) as well as β-Catenin independent (WNT5A driven) Wnt signaling (canonical versus non-canonical) have been described in the context of cancer and melanoma." (PMID 39562548, 2024). "In melanoma, studies have shown that AXL expression was positively correlated with WNT5A." (PMID 36646673, 2023). "In a BRAFV600E PTEN–/– melanoma mouse model, expression of the non-canonical WNT5A was upregulated upon immune checkpoint inhibition with a PD-1-targeting antibody." (PMID 36982422, 2023). "WNT5A binds to Frizzled 4-LRP6 complex to activate ARF6, which leads to the separation of β-catenin and N-cadherin, resulting in free β-catenin into nucleus, and ultimately promotes the metastasis of melanoma cells." (PMID 37716993, 2023). "Several of the EMT-related genes with higher expression in NR patients encoded for molecules controlling adhesion (ITGB3, VCAM1, collagens, and others), interaction with extracellular matrix (VEGFA, MMP14, WNT5A, LAMA1, and others), and melanoma de-differentiation (KRT9, KRT10, EGFR, and others)." (PMID 37739939, 2023). "In contrast, non-canonical WNT-driven tumors such as melanoma and gastric cancer overexpress non-canonical ligand WNT5a and its co-receptor ROR1." (PMID 36612190, 2022). "Furthermore, WNT5A activates SNAIL and induces the EMT, subsequently promoting tumor metastasis in melanoma and ovarian cancer." (PMID 35595735, 2022).
melanoma (continued). "Interestingly, these results suggest that the regulatory roles of WNT5A and IL-6 in MARCKS expression and activation are lost during the acquisition of BRAFi resistance in melanoma cells." (PMID 36551563, 2022). "Most of our knowledge about the role of non-canonical WNT signaling pathway in melanoma came from the studies on WNT5A." (PMID 36620565, 2022). "Recently, we reported that the PKC substrate MARCKS is required for WNT5A-induced invasion of melanoma cells that have not been exposed to a BRAFi and consequently have not developed any resistance to the drug." (PMID 36551563, 2022). "To date, the role of MARCKS and its relation to WNT5A have not been explored in highly metastatic BRAFi-R melanoma cells." (PMID 36551563, 2022). "Consistently, Wnt5A, a non-canonical Wnt protein, regulates Ca2+–dependent EVs release in an auto- or paracrine manner in malignant melanoma cells and enhances exosome release during Wnt5a/PI3K/miR-122 mediated hepatocyte differentiation." (PMID 36435789, 2022). "WNT5A is a key WNT-signaling family member that has been extensively studied for its role as a tumor promoter in melanoma, with a documented ability to enhance melanoma cell migration, invasion and metastasis." (PMID 36551563, 2022). "The non-canonical wingless-related integration site 5a (Wnt5a) is a homolog of Wingless proteins in Drosophila species, which is secreted by cancer cells such as melanoma cells." (PMID 33919546, 2021). "Although there have been numerous reports suggesting that WNT5A plays an essential role in melanoma invasion, the exact mechanism whereby WNT5A regulates this progressive behavior of melanoma cells has not been fully elucidated." (PMID 33969605, 2021). "Wnt5A is a non-canonical Wnt ligand that drives a metastatic, therapy-resistant phenotype in melanoma." (PMID 33578751, 2021). "We compared melanoma cells with low (HTB63 cells) and high (WM852 cells) WNT5A expression." (PMID 33969605, 2021). "Interestingly, two of the cell lines in the present study (A375 and UACC903) were used to demonstrate that Wnt5a and ROR1 activate Akt suggesting that both ROR receptors have antagonistic roles on the activation of Akt in melanoma." (PMID 34774050, 2021). "The noncanonical Wnt ligand Wnt5a has, for example, been shown in melanoma to induce the secretion of Exos enclosing the in this context immunomodulatory factor IL‐6 and proangiogenic VEGF and MMP2." (PMID 33207034, 2021). "Recent studies have shown the role of noncanonical Wnt5A-mediated signaling in melanoma cellular processes through calcium-dependent enzymes." (PMID 33647315, 2021). "Our results demonstrate that WNT5A-induced phosphorylation of MARCKS is not only an indicator of PKC activity but also a crucial regulator of the metastatic behavior of melanoma and therefore an attractive future antimetastatic target in melanoma patients." (PMID 32033033, 2020). "Moreover, under the influence of Wnt5a, DCs upregulate the expression and activity of IDO and, thus, drive Treg differentiation, which serves to repress melanoma immune surveillance." (PMID 33171792, 2020). "Next, we employed a peptide inhibitor of MARCKS phosphorylation that did not affect MARCKS expression and found that it abolished WNT5A-induced melanoma cell invasion." (PMID 32033033, 2020). "Our observation of a decreased F-actin content at the cell edge suggests that WNT5A signaling by phosphorylating MARCKS interferes with the MARCKS F-actin binding ability and destabilizes the F-actin network at the cell edge to favor melanoma cell invasion." (PMID 32033033, 2020). "Since MARCKS phosphorylation is important for the control of actin dynamics, our novel observations of PKC and RhoA-ROCK signaling being involved in melanoma cell invasion mediated by WNT5A-induced MARCKS phosphorylation, suggest the importance of these signaling pathways in melanoma." (PMID 32033033, 2020).
melanoma (continued). "In line with this, high level of WNT5a, which regulates the activity of non-canonical WNT signaling pathway, and low level of β-catenin were associated with increased basal autophagy in melanoma cells." (PMID 32340261, 2020). "The induction of the noncanonical Wnt pathway by BMI1 was also observed in melanoma cells that were resistant to the treatment of BRAF inhibitor by the upregulation of the Wnt5a and ROR2 receptors." (PMID 32726929, 2020). "The question then arises concerning if and how IL‐6 and WNT5A will affect migration and invasion of BRAFi‐R melanoma cells in the absence of an IL‐6/WNT5A positive feedback loop." (PMID 30582770, 2019). "Since these melanoma cells are not Wnt5a treated, this dramatic increase in APT1S209D melanoma invasion is due to the single point mutation that mimics phosphorylation alone." (PMID 29648538, 2018). "Wnt5a signaling results in acyl protein thioesterase 1 (APT1) mediated depalmitoylation of pro-metastatic cell adhesion molecules CD44 and MCAM, resulting in increased melanoma invasion." (PMID 29648538, 2018). "For example, in contrast to melanoma cells, WNT5A-treated breast cancer cells do not respond with an increase in aerobic glycolysis but instead with a significant increase in their oxygen consumption rate (OCR)." (PMID 29069720, 2017). "Unlike melanomas in which WNT5A triggers tumor-promoting effects including a positive regulation of aerobic glycolysis, we expected an opposing effect in breast cancer cells where WNT5A is predominantly considered to exert tumor suppressor functions." (PMID 29069720, 2017). "WNT-5A and LDH5 expression levels positively correlate in melanoma patient tissue samples." (PMID 26514730, 2016). "Wnt5a, best characterized as a non-canonical signaling ligand, has been shown to promote melanoma invasion in a PKC-dependent manner, signaling through Fzd5." (PMID 27589803, 2016). "WNT3 and WNT5A were detected at a much higher level than WNT8 and WNT11, so we investigated further whether WNT3 and WNT5A signal through FZD7 in melanoma cells." (PMID 26808375, 2016). "This demonstrated a direct link between Wnt5a levels and SOCE in melanoma cells." (PMID 27417567, 2016). "Additionally, canonical signaling through Wnt5a has been shown to promote ARF6 activation and subsequent melanoma invasion by stimulating β-catenin-mediated transcriptional activity." (PMID 27589803, 2016). "Previous studies showed that Wnt5A requires ROR2 expression to mediate the migration of cells during mammalian palate development and that increased expression of Wnt5A led to increased melanoma cell motility." (PMID 28536612, 2016). "FZD7-knockdown led to attenuated phosphorylation of JNK in both knockdown cell lines, suggesting that FZD7 trasmits non-canonical WNT signaling from WNT5A in melanoma cells." (PMID 26808375, 2016). "For example, Wnt-5a is increased in melanoma, colorectal cancer, pancreatic cancer, non-small cell lung cancer, renal cell carcinoma and glioma." (PMID 26895946, 2016). "In support of our finding of a WNT5A-IL-6 positive feedback loop, both WNT5A and IL-6 have been reported to promote tumour cell metastasis, although the role of IL-6 has not been completely explored in melanoma." (PMID 27191257, 2016). "In line with this idea a modest increase of WNT5a in over-confluent melanoma cells was observed also in other cell lines (data not shown)." (PMID 27175588, 2016). "This assumption is supported by the demonstration that nuclear WNT5A is not important in predicting survival in melanoma patients." (PMID 26393652, 2015). "Remarkably however, the absence of MITF marks a AXL+/WNT5A+ population of melanoma cells – previously identified as the ‘Hoek's invasive signature cohort’ – that is unresponsive to MAPK pathway inhibitors." (PMID 25818589, 2015).